MEN1 (menin 1)
Diseases named in the same sentence as MEN1 in open-access papers (continued):
Sharing a sentence is not in itself a finding about the gene and the disease.
insulinomas (continued). "We and our collaborators have previously demonstrated that menin physically interacts with β-catenin, and that Men1 deficiency leads to nuclear translocation and activation of the latter in mouse Men1 insulinoma." (PMID 34446068, 2021). "Insulinomas occur in approximately 20–30% of cases, with a metastatic process being observed in 4–14% of MEN1 patients." (PMID 33807230, 2021). "Mice bearing a germline heterozygous inactivation of the Men1 gene are a representative model of MEN1 in humans; these animals developed hyperplasia and/or tumors of the pancreatic beta cells (mainly insulinoma), starting at 8 to 12 months of life." (PMID 33919851, 2021). "Here, we present the case of a 34-year-old male with recurrent hypoglycemic episodes and hyperparathyroidism diagnosed with multiple pancreatic insulinomas secondary to MEN1." (PMID 32577326, 2020). "YY1 was shown to be recurrently mutated in insulinomas, while mutations in ATRX/DAXX/MEN1 are very uncommon." (PMID 32512761, 2020). "Insulinomas from subjects known to be members of MEN1 kindreds were intentionally excluded, although one insulinoma (Ins_27) was derived from a subject with a MEN1 mutation." (PMID 33060578, 2020). "MEN1 insulinomas usually manifest as single benign lesions, often sized >1 cm, in the setting of multiple islet macroadenomas." (PMID 33312161, 2020). "Nevertheless, the distinction of the insulinoma(s) from other NF-pNET lesions in the context of MEN1 is challenging." (PMID 32947997, 2020). "In line with previous studies, ENETS consensus guidelines already recommended MEN1 genetic testing in patients with insulinoma before 20 years." (PMID 31044390, 2019). "Insulinomas are the second most common type of functional enteropancreatic neoplasm in patients with MEN1, representing 10–30% of pNETs in this group." (PMID 31263451, 2019). "A previous study in MEN1 mutant mice showed a reduction of p27kip1 protein expression in 77% of insulinomas." (PMID 29853883, 2018). "Most insulinomas occur sporadically or, less frequently, as part of familial cancer syndromes, including multiple endocrine neoplasia type 1 (MEN1), von Hippel Lindau syndrome, neurofibromatosis, and tuberous sclerosis complex." (PMID 29853883, 2018). "Insulinomas are the second most common GEP-NETs in MEN1, manifesting in 10–30% of patients, often as multiple tumours." (PMID 30428914, 2018). "We performed whole-exome sequencing (WES) on three parathyroid tumors, one pancreatic insulinoma, and a blood sample taken from the same patient with MEN1 to study tumor heterogeneity in MEN1 originating from different tumors." (PMID 28969599, 2017). "Approximately 10% of patients with MEN1 will develop insulinomas, and in these cases the tumours are more likely to be multiple and more likely to recur." (PMID 28965289, 2017). "The β-cell-specific knockout of Men1 (βMen1-KO) leads to the development of benign insulinomas in mice." (PMID 25517963, 2014). "Insulinoma in MEN1 are uncommonly malignant with extrapancreatic infiltration and/or metastasis (2.4%–17.9% with an average of 8.4%)." (PMID 24213321, 2012). "Hypoglycemic syndrome in MEN1 patients usually occurs in the second or third decade of life, one decade earlier than patients with sporadic insulinomas." (PMID 24213321, 2012). "Since sporadic insulinoma is usually a solitary lesion, if multiple pancreatic nodules are identified, a MEN1 diagnosis should be considered." (PMID 24213321, 2012). "In MEN1 insulinoma, the possible simultaneous presence of multiple pancreatic nodules makes it difficult to localize the lesion responsible for the increased insulin overproduction." (PMID 24213321, 2012). "When managing pediatric insulinomas, we need to consider the involvement of MEN1." (PMID 41199767, 2025). "Coexistence of glucagonomas and insulinomas has been reported in adults, mostly with MEN1." (PMID 40941664, 2025).
insulinomas (continued). "Aside from PHPT, there were no clinical features of other MEN1-associated tumors, such as symptoms of gastrinoma (for example, peptic ulcer disease) or insulinoma (for example, hypoglycemia)." (PMID 41272807, 2025). "In individuals with MEN1, roughly 8% of insulinomas are malignant." (PMID 39201946, 2024). "As mentioned, the retrospective study on 55 Chinese patients with MEN1-related insulinoma (52% males and 47% females) showed that 78% of them had primary hyperparathyroidism, 69% were associated with pituitary tumors, and 16% were confirmed with an adrenal tumor." (PMID 38928056, 2024). "Insulinomas occur with an incidence of 10–15% in patients with MEN1 and may develop at a very young age." (PMID 38893191, 2024). "These included 76 (54%) nonfunctioning pNENs and 64 (46%) functioning pNENs (30 insulinomas, 24 gastrinomas, 10 rare pNENs), which were sporadic in 94 (67%) cases and associated with MEN1 (Multiple Endocrine Neoplasia 1) in 46 (33%) cases." (PMID 37771441, 2023). "These MEN1 mutations are more frequent in gastrinomas (37%), VIPomas (44%), and glucagonomas (67%), while less frequent in insulinomas and nonfunctioning PanNETs (8%)." (PMID 37623030, 2023). "Cre targeting of MEN1 in pancreatic progenitor cells using a Pdx1-Cre recombinase demonstrated endocrine only pancreatic insulinoma development at 10–12 months, resulting from increased VEGF expression, which could be reduced by anti-VEGF therapy." (PMID 37568572, 2023). "Interestingly, all of our patents had insulinoma as the first MEN1 manifestation, while other components of the syndrome developed later in life." (PMID 37152923, 2023). "Additionally, if a patient is diagnosed with insulinoma before the age of 20 or with multiple insulinomas at any age, MEN1 should also be suspected, and patient screened." (PMID 36950054, 2023). "The other patient with high malignancy-potential insulinoma in our cohort (case #20; no MEN1 mutations) presented with multiple pancreatic lesions, requiring pancreatic gastroduodenal resection, but distant metastases were found eight years after the surgery." (PMID 37152923, 2023). "Furthermore, the knockdown of MEN1 was responsible for the down-regulation of caspase 8 activity in human insulinoma cells and human pancreatic stellate cells." (PMID 34878630, 2022). "Therefore, it is important to screen for MEN1 in patients with insulinoma, especially younger patients, and to obtain a correct diagnosis before the appearance of overt symptoms." (PMID 35698198, 2022). "In addition, 13 (23.6%) patients with insulinoma only as their first presentation developed other manifestations of MEN1 after a median of 3 years (range 1–26 years)." (PMID 35698198, 2022). "Insulinoma was the first manifestation of MEN1 in at least 23.6% (13/55) of patients." (PMID 35698198, 2022). "Patients with insulinoma of MEN1 often experience hypoglycemia-induced syncope, which affects their daily life and could be life-threatening." (PMID 35954231, 2022). "Additionally, the accumulation of the anti-apoptotic FlipS isoform confirmed that MEN1 knockdown impedes cell demise, especially in human insulinoma cells." (PMID 34878630, 2022). "68Ga-DOTATATE PET/CT imaging may be an available nuclear imaging tool for the detection of MEN1-related tumors and preoperative localization of small and low-grade insulinomas by PET/CT." (PMID 36042606, 2022). "Hypermethylation of promoters of RASSF1 and MGMT genes appears to be an epigenetic marker of MEN1 insulinomas or MEN1 NF-pNETs, respectively, suggesting that they could be promising selective therapeutic targets for these two types of pancreatic tumors." (PMID 33919851, 2021). "This phenomenon is not related to mutation in MEN1 gene and is more similar to sporadic benign insulinomas." (PMID 34737724, 2021).
insulinomas (continued). "With regards to molecular genetics, this phenomenon is not related to mutation in MEN1 gene and is more similar to sporadic benign insulinomas, however, at the moment molecular genetics of this disease remains poorly investigated." (PMID 34737724, 2021). "Insulinomas are the most common functional pNETs in MEN1, observed in 18% of MEN1 patients." (PMID 34680266, 2021). "With regards to molecular genetics, this phenomenon is not related to mutation in MEN1 gene and is more similar to sporadic benign insulinomas, however, large-scale molecular genetic studies on this disease have not yet been carried out." (PMID 34737724, 2021). "A great majority of MEN1 patients develop, during their life, multiple pancreatic microadenomas (less than 0.5 cm in diameter), mostly NF-pNETs (approximately 50% of cases), insulinomas (7–31% of cases), and gastrinomas (about 5% of cases)." (PMID 33919851, 2021). "Additionally, α-cell-specific Men1 knockout in mice leads to the development of glucagonomas, which evolve into mixed glucagonoma/insulinoma to ultimately become insulinomas, possibly via trans-differentiation of the Men1-deleted α-cells." (PMID 33288854, 2020). "The surgical indication of MEN1 related insulinomas is systematic." (PMID 32947997, 2020). "Among sporadic PNETs, 44% of non-functional tumors show MEN1 mutations, and the prevalence of a MEN1 mutation in functional tumors is as follows: glucagonoma (60%), VIPoma (57%), gastrinoma (38%), and insulinoma (2%–19%)." (PMID 33537001, 2020). "Indeed, early inactivation of Men1 specific to beta-cells leads to multiple insulinoma only by 60 weeks, suggesting the requirement of additional somatic events." (PMID 33101198, 2020). "In the context of MEN1, insulinomas are the second most prevalent functioning pancreatic tumor." (PMID 33312161, 2020). "Men1 knock-out mice provide a model of insulinoma, in which tumors develop late." (PMID 33101198, 2020). "In this setting, non-conservative surgery is mainly preferred in the case of MEN1 related insulinoma associated with other pNETs." (PMID 32947997, 2020). "Notably, in Men1 knock-out tumors, an increase in the number of entire chromosome 11 was also found in insulinomas, and of chromosome 15 in pituitary prolactinomas." (PMID 33101198, 2020). "Insulinomas occur on a background of MEN1 in less than 5% of the cases." (PMID 32947997, 2020). "The most common histological type of MEN1-associated GEP-NET was insulinoma (47.4%), followed by non-functioning pancreatic adenoma (31.6%) and gastrinoma (15.8%), with an overall penetrance of 33.3%, 22.2% and 11.1% among MEN1 patients, respectively." (PMID 31044390, 2019). "In recently published work, mutations in Men1, Daxx, and Atrx were shown to be less common in human insulinomas than in human nonfunctioning tumors, suggesting that subtypes of PanNETs are influenced by the presence of these driver mutations." (PMID 30796198, 2019). "Moreover, the MEN1 gene is the first gene that has been identified as a candidate gene in the tumorigenesis of insulinoma." (PMID 29435419, 2018). "Nearly 10% of insulinomas occur in the context of MEN1, an autosomal dominant disorder." (PMID 29921249, 2018). "Insulinoma is not an infrequent cause of hypoglycemia in adolescents and its presence should always prompt consideration of MEN1." (PMID 28663159, 2017). "On average insulinomas in patients with MEN1 present one decade earlier than sporadic cases." (PMID 28965289, 2017). "Insulinoma appears to be more common in Asian patients with MEN1." (PMID 28965289, 2017). "Insulinoma is only occasionally the presenting feature of MEN1." (PMID 28965289, 2017). "All patients with a family history of MEN1 associated conditions, all patients with multiple or duodenal as well as or in the absence of pancreatic gastrinomas and all patients presenting with insulinoma before the age of 40 should be strongly suspected to have MEN1 and screening be considered." (PMID 28965289, 2017).
insulinomas (continued). "MHPT patients could be diagnosed earlier than SHPT patients due to other MEN1 related endocrinopathies (such as insulinoma and pituitary functional adenoma)." (PMID 27846313, 2016). "We reported an extremely rare case of giant insulinoma and simultaneous occurrence of pheochromocytoma and adrenal cortical adenoma in the ipsilateral adrenal gland in a patient clinically and genetically diagnosed as having MEN1." (PMID 27572829, 2016). "In conclusion, we reported an extremely rare case of a giant insulinoma and simultaneous occurrence of pheochromocytoma and adrenal cortical adenoma in the ipsilateral adrenal gland in a patient clinically and genetically diagnosed as having MEN1." (PMID 27572829, 2016). "In contrast, nol3 deletion affected neither basal rates of cell proliferation nor cell death in MEN1 insulinomas, which likely accounts for the absence of an effect of loss of ARC in these tumors." (PMID 26709830, 2015). "Parathyroid tumors are the first manifestation of MEN1 in more than 85% of patients, and in the remaining fewer than 15% of patients, the first manifestation may be an insulinoma or a prolactinoma." (PMID 23933118, 2014). "Different from sporadic insulinomas, enucleation or limited resection of pancreatic nodules in MEN1 patients may lead to the persistence of hypoglycemia." (PMID 24213321, 2012). "Therefore, when MEN1 insulinomas are located in the left pancreas, the proposed treatment should be distal pancreatic resection up to the superior mesenteric vein, associated with enucleation of any additional tumors in the pancreatic head." (PMID 24213321, 2012). "Somatic MEN1 mutations are observed in 30% of the common sporadic counterparts (e.g., parathyroid adenoma, gastrinoma, insulinoma and bronchial carcinoid) of the endocrine tumor types seen in familial MEN1, except in sporadic pituitary tumors (only 1–5% with MEN1 mutation)." (PMID 22666422, 2012). "Insulinomas in MEN1 are generally benign (90%) and occur in about 15–20% of affected patients." (PMID 24213321, 2012). "Therefore, GLP-1R PET/CT may be a helpful tool in differentiating insulinomas from other PanNETs present in MEN1 patients and guiding successful surgical intervention, albeit it is does not seem to be useful in metastatic insulinomas." (PMID 38893191, 2024). "Finally, although there are no established individual models for pNENs, canine insulinomas mimic the sporadic, long-term development nature of humans and have similar mutations including MEN1, ATRX, and in SSTR2 expression." (PMID 37568572, 2023). "No MEN1 mutation was identified in this patient indicating possible presence of other important genetic events like involvement of other unidentified gene/s, chromosomal instability resulting in insulinoma development, and probably the presence of phenocopies." (PMID 26307114, 2015). "While heterozygous knock-out of MEN-1 in mice results in a good model for the disease, the complexity of menin function was recently underlined by the investigation of rodent islets after α-cell specific knock out of MEN-1, which resulted in the formation of glucagonomas and insulinomas." (PMID 24281208, 2010). "Thus, in late presentation cases, we can assume that 18F-DOPA PET-CT should be performed only to exclude insulinoma, since it can occur at any age, but is very rare in pediatric age, and could represent a manifestation of Multiple endocrine neoplasia type 1 (MEN1)." (PMID 32928245, 2020). "In other mouse models of PanNETs21,24,25, MEN1 deletion using the insulin or PDX1 promoter driven Cre construct, insulinomas, glucagon-expressing tumors and well differentiated PanNETs were also observed." (PMID 30315258, 2018). "While inactivation or loss of the trithorax complex member, menin, encoded by MEN1, is a well-known cause of insulinoma in mice and humans, the striking prevalence of mutations and/or dysregulation in many other trithorax and polycomb members in non-MEN1 insulinomas was not anticipated." (PMID 28974674, 2017).
insulinomas (continued). "However, we did not detect a somatic MEN1 gene mutation or LOH in the pancreatic insulinoma." (PMID 28969599, 2017). "Although insulinomas, gastrinomas, glucagonomas, and non-functional pancreatic NETs have been grown in MEN1-mutant, RIP-Tag, and Glu-Tag murine models, there are no accounts of siNET generation." (PMID 39649120, 2024). "Although multiple insulinomas in MEN1 patients are reported in the literature, we did not yet observe this condition in our MEN1 cohort of over 100 patients." (PMID 37386194, 2023). "The GLP-1R-negative, MEN1-related insulinoma did not metastasize during the follow-up of over 20 years." (PMID 37894845, 2023). "As only two patients had a MEN1-related insulinoma, one expressing and the other one not expressing GLP-1R, we were not able to draw conclusions from the GLP-1R expression of MEN1-related insulinomas in general." (PMID 37894845, 2023). "This cohort included two MEN1-related insulinomas, of which one expressed GLP-1R and the other one did not." (PMID 37894845, 2023). "Insulinoma showed a major rate of hypermethylation among the other subgroups of functioning PanNENs, especially in epigenetic modifying enzymes as INS/IGF2 locus, CDNK1C, MEN1, KDM6A, MLL3/KMT2C, YY1, KDM5B, and SMARCC1." (PMID 36830839, 2023). "A review of the course of disease course revealed that all patients were diagnosed with MEN1 after the discovery of insulinoma, and none of them were screened for MEN1 beforethe diagnosis of insulinoma, including three patients with a family history of MEN1." (PMID 35698198, 2022). "Given the history and presentation of our case, we recommend that the clinicians consider the possibility of autonomous cortisol production in MEN1 patients who do not show severe symptoms of hypoglycemia in the presence of insulinoma." (PMID 35448982, 2022). "Children with MEN1 most frequently present with pituitary (prolactin-secreting) and pancreatic (gastrinomas, insulinomas, and non-functional) NENs, in addition to primary hyperparathyroidism which is not currently classified as an NEN." (PMID 36291833, 2022). "The most common form of functioning NET is gastrinoma, as in MEN1, while no cases of VIPomas, glucagonomas, insulinomas, or somatostatinomas have been reported so far." (PMID 35355569, 2022). "Moreover, in mouse insulinomas, decreased MAFA expression resulting from targeted MEN1 ablation was consistently observed." (PMID 35406570, 2022). "Moreover, a relationship between MEN 1 and MAFA genes was also established: altered MEN1 expression was shown to disrupt the MAFA differentiation pathway in human and mice insulinoma cells." (PMID 33101198, 2020). "Of the two patients without hypoglycemic symptoms prior to the diagnosis of insulinoma, one was found in connection with the MEN1-investigations of the patient's sibling, and the symptoms related to hypoglycemia first appeared 3 years after the diagnosis." (PMID 30425741, 2018). "This is in line with studies confirming that insulinomas in particular present at young age in patients with MEN1, as opposed to gastrinomas." (PMID 30254610, 2018). "We report herein a case of MEN1 with a giant insulinoma of the pancreatic tail, non-functional adrenal cortical adenomas, and an ipsilateral pheochromocytoma." (PMID 27572829, 2016). "Especially in ectopic or small lesions below a size of 1 cm and in MEN1 patients who sometimes suffer from multiple insulinomas or if preoperative imaging does not at all or not correctly show the lesion the benefit for our patients is high." (PMID 26034506, 2015). "Studies in a cohort of 126 mice demonstrated that, although mice lacking Men1 developed insulinomas as expected, elimination of ARC in this context did not significantly alter tumor load." (PMID 26709830, 2015). "We conclude that ARC does not appear critical in the pathogenesis of insulinomas in this mouse model of MEN1." (PMID 26709830, 2015).